H19 (H19 imprinted maternally expressed transcript)
Diseases named in the same sentence as H19 in open-access papers (continued):
Sharing a sentence is not in itself a finding about the gene and the disease.
seminoma (8 papers, 2016 to 2023). A radiosensitive malignant germ cell tumor found in the testis (especially undescended), and extragonadal sites (anterior mediastinum and pineal gland). "As expected, the level of miRNA‐106b‐5p was negatively associated with TDRG1 expression in seminoma (P < 0.05), while H19 showed a positive correlation with TDRG1 expression (P < 0.05)." (PMID 30430771, 2018). "More interestingly, seminoma stands at the crossroads of developmental and neoplastic processes, which, at least partially, explains our findings that H19 is overexpressed in seminoma." (PMID 30430771, 2018). "Combining the previous results, we demonstrated that H19 promoted the expression of TDRG1 by sequestering miRNA‐106b‐5p in seminoma cells." (PMID 30430771, 2018). "Due to the difficult nature of collecting tumor tissues from CDDP‐resistant seminoma patients, it was challenging to directly compare the levels of H19, miRNA‐106b‐5p, and TDRG1 between primary tumors and their CDDP‐resistant counterparts." (PMID 30430771, 2018). "To detect H19 and miRNA‐106b‐5p expression in seminoma, we collected 10 specimens from seminoma patients and 10 specimens of normal testicular tissues." (PMID 30430771, 2018). "In this study, we compared the transcriptome of a newly established CDDP‐resistant seminoma TCam‐2 cells and their parental origins so as to define two differentially expressed ncRNAs—miRNA‐106b‐5p and lncRNA H19." (PMID 30430771, 2018). "By performing bisulfite colony sequencing for the H19‐IC region, we found intermediate methylation levels of 39% in the seminoma, as would be expected if resetting of imprints in the germ line has not yet commenced." (PMID 30003711, 2018). "The H19/miRNA‐106b‐5p/TDRG1 axis was validated in homeostatic seminoma as well as in a CDDP‐resistant context." (PMID 30430771, 2018). "Furthermore, the H19/miR-NA-106b-5p/NDRG1 axis was recently identified as a potential target for the treatment of seminoma and CDDP-resistant cancers." (PMID 36902032, 2023). "Together, these results support the idea that H19 provides seminoma cells with an ability to survive under CDDP treatment, which may be determined by the “sponge” effect to sequester miRNA‐106b‐5p." (PMID 30430771, 2018). "Collectively, these results indicated that H19 might function as an endogenous miRNA‐106b‐5p sponge in seminoma cells." (PMID 30430771, 2018). "As TDRG1 can regulate sensitivity of CDDP in seminoma cells, we hypothesized that both H19 and miRNA‐106b‐5p may play important roles in CDDP resistance." (PMID 30430771, 2018). "Second, hypomethylation of chromosome 11p15.5, which occurs in 38.5% of RSS cases and leads to hypomethylation of the IGF2/H19 imprinting control region (ICR), may be a risk factor for seminoma." (PMID 27034882, 2016). "Furthermore, the newly identified H19/miRNA‐106b‐5p/TDRG1 axis may serve as a potential target for the treatment of seminoma and the CDDP‐resistant tumors." (PMID 30430771, 2018). "However, more evidence is still needed to uncover the tumorigenic property of H19 in seminoma." (PMID 30430771, 2018). "The H19/miRNA-106b-5p/TDRG1 axis was confirmed in a CDDP-resistant environment and in homeostatic seminoma." (PMID 36902032, 2023). "In this way, H19 would directly lead to TDRG1 upregulation, leading to seminoma cisplatin resistance." (PMID 33767982, 2021). "In summary, our studies demonstrated that elevated H19 and decreased miRNA‐106b‐5p expression are correlated with CDDP resistance in seminoma cells." (PMID 30430771, 2018). "However, whether H19 can attract miRNAs other than miRNA‐106b‐5p in seminoma is still unclear." (PMID 30430771, 2018). "H19‐IC, as opposed to the PW‐IC, is hypomethylated in virtually all seminomas with the exception of spermatocytic seminomas which originate from mature germ cells, rather than from a primordial germ cell." (PMID 30003711, 2018).
seminoma (continued). "In addition, DNA methylation status of the PWS‐ and H19‐ imprinting centers in wild‐type and affected fibroblasts, patient derived induced pluripotent stem cells (iPSCs), and PWS seminoma were determined by bisulfite DNA colony sequencing." (PMID 30003711, 2018). "Moreover, our findings confirmed a strong association between oligozoospermia and imprinting defects (herein, on H19/IGF2, MEG3/DLK1, and SNURF DMRs for oligozoospermic patients with or without seminoma)." (PMID 30340650, 2018).
abdominal aortic aneurysm (7 papers, 2019 to 2025). Enlargement and ballooning of the vessel that supplies arterial blood to the abdomen, pelvis and legs. "In contrast to our results, a prior investigation by Li and colleagues using pigs to evaluate lncRNA H19 showed that its expression was really elevated in two mice models of abdominal aortic aneurysm using a low-density lipoprotein receptor mutant pig model." (PMID 37259407, 2023). "The expression of H19 is significantly higher in the abdominal aorta samples of mouse abdominal aortic aneurysm (AAA) model than in normal aortic tissues." (PMID 33403385, 2021). "Only H19 lncRNA has been tested in pigs to prove the expression of lncRNA H19 increased in two abdominal aortic aneurysm mouse models by a low‐density lipoprotein receptor knockout pig model." (PMID 32896990, 2020). "For instance, Li and colleagues demonstrated that H19 exerted proapoptotic and anti-proliferative effects in HA-VSMCs leading to subsequent abdominal aortic aneurysm development." (PMID 32219038, 2020). "The long non‐coding RNA H19 silencing significantly suppressed HASMC apoptosis and phenotype switching in patients with abdominal aortic aneurysms." (PMID 39219022, 2025). "In the latest research, in a mouse model of abdominal aortic aneurysm (AAA), H19 overexpression in VSMCs increased IL-6 expression, promoted vascular inflammation, and ultimately induced AAA development." (PMID 34344446, 2021).
biliary atresia (7 papers, 2020 to 2026). A rare, biliary tract disease characterized by progressive obliterative cholangiopathy of the intra- and extrahepatic bile ducts, occurring in the embryonic/ perinatal period, leading to severe and persistent neonatal jaundice and acholic stool. "In short, the serum exosomal H19 may serve as a novel non-invasive therapeutic target and diagnostic biomarker for biliary atresia." (PMID 37326156, 2023). "Regarding lncRNAs, in subjects with biliary cholangitis and biliary atresia, there is a reported correlation between the severity of fibrotic liver injury and the level of EV-carried lncRNA H19 in the serum." (PMID 38540698, 2024). "Moreover, in biliary cholangitis and biliary atresia patients, the serum level of EV-carried H19 was found to correlate with the severity of fibrotic liver injury." (PMID 38540698, 2024). "Previous studies have demonstrated that expression levels of lncRNA H19 are elevated in PSC and biliary atresia patients." (PMID 32154257, 2020).
bladder tumors (7 papers, 2010 to 2018). "Increasing evidence suggests that H19 is abnormally expressed in breast, liver, lung, cervical, esophageal, and bladder tumors, and promotes cancer cell proliferation, suggesting an oncogenic function." (PMID 27765929, 2016). "However, several other studies have shown that H19 characterized as oncogenic factor in breast adenocarcinoma, bladder tumor and choriocarcinoma." (PMID 24466011, 2014). "Our findings show that bladder tumors may be successfully treated by intravesical instillation of the double promoter vector H19-DTA-P4-DTA." (PMID 21162716, 2010). "The therapeutic potency of the vector was tested by 3 intratumoral injections, at two-day intervals, of 25 μg of H19-DTA-P4-DTA or of the control vector (H19-Luc-P4-Luc), into each heterotopic bladder tumor." (PMID 21162716, 2010). "The therapeutic potency of the vectors was tested by direct intratumoral injection of 25 μg of the DTA expression vectors (H19-DTA, P4-DTA, or H19-DTA-P4-DTA), or of the control vectors (H19-Luc, P4-Luc, or H19-Luc-P4-Luc) into each heterotopic bladder tumor." (PMID 21162716, 2010).
choriocarcinoma (7 papers, 2012 to 2022). An aggressive malignant tumor arising from trophoblastic cells. "HOTS (H19 opposite tumor suppressor), an H19 antisense transcript, is confirmed to inhibit tumor growth in rhabdomyosarcoma and choriocarcinoma." (PMID 36246634, 2022). "H19 knockout inhibited the proliferation, migration and invasion and promoted the apoptosis of choriocarcinoma-resistant cells." (PMID 34977037, 2021). "Aside from the altered H19 expression observed in placentas from complicated pregnancies, H19 is down-regulated when a hydatiform mole transitions to choriocarcinoma." (PMID 28653993, 2017). "To further clarify our understanding of the function of the H19 gene in choriocarcinoma, we developed lentiviral vectors expressing H19-specific small interfering RNA (siRNA) for use in human choriocarcinoma cells." (PMID 23711233, 2013). "H19 is also related to the drug resistance of choriocarcinoma (CC)." (PMID 36246634, 2022). "Yu and colleagues showed that H19 is related to the drug resistance mechanism of choriocarcinoma." (PMID 34977037, 2021). "The finding that H19 downregulation could simultaneously inhibit proliferation and apoptosis of JAR cells highlights a putative dual function for H19 in choriocarcinoma and may explain the debate on whether H19 acts as a tumor suppressor or a tumor promotor in trophoblast tissue." (PMID 23711233, 2013).
gastric tumor (7 papers, 2013 to 2023). "Consistent with our data, the lncRNAs H19, GAS5, TUG1, AP5M1, and MALAT1 were found to be overexpressed in TCGA database gastric tumors." (PMID 29719612, 2018). "Consistent with our results, we also found overexpression of lncRNAs such as H19, GAS5, TUG1, AP5M1 and MALAT1 and downregulation of LINCROR, POU3F3, HOTAIR, FALEC, NBAT1, and ZEB2-AS1 lncRNAs in TCGA gastric tumor datasets." (PMID 29719612, 2018). "The RNA-Seq results from the public database TCGA-TANRIC database showed that MALAT1, H19, and TUG1 were among the top twenty overexpressed lncRNAs in gastric tumors." (PMID 29719612, 2018).
hyperhomocysteinemia (7 papers, 2010 to 2024). A serious metabolic condition caused by mutations in the MTHFR gene, medications, or nutritional deficiency. "Moreover, it has been observed that imprinted gene H19 is hypermethylated, not hypomethylated, in brain and aorta of hyperhomocysteinemic mice, although the effect of hyperhomocysteinemia on H19 DMD methylation was tissue-specific in these mice." (PMID 20300621, 2010).
renal cell carcinoma (7 papers, 2013 to 2024). "The long non-coding RNA (lncRNA) H19 has been demonstrated to play a crucial role in carcinogenesis, including renal cell carcinoma (RCC)." (PMID 32509581, 2020). "The lncRNA H19 regulates GLIOMA angiogenesis, while MAP3K14 is one of the well-recognized biomarkers in the prognosis of renal cancer, which is reminiscent of the pancreatic metastasis from renal cell carcinoma." (PMID 38741200, 2024).
aneurysm (6 papers, 2020 to 2023). Bulging or ballooning in an area of an artery secondary to arterial wall weakening. "Recent study revealed a pathogenic H19 induce aneurysm by inflammatory pathway related to the formation of AAA, and this has offered a novel treatment for AAA." (PMID 34620091, 2021). "The expression of MALAT1 and H19 is significantly increased in atherosclerotic lesions and aneurysm tissues." (PMID 37568514, 2023). "Knockdown of H19 using antisense oligonucleotides led to a significant reduction of aneurysm formation in two different murine AAA models." (PMID 31989839, 2020). "In addition to intracranial aneurysm, H19 levels were up-regulated in aneurysm biopsies taken from patients with abdominal aortic aneurysm (AAA) as compared with the abdominal aortic tissue from healthy controls." (PMID 35946958, 2022). "In addition, lncRNA H19 has been found to be upregulated in Ang II and PPE induced AAA animal models, and knockdown of H19 inhibited the aneurysm formation in both AAA models." (PMID 35207478, 2022). "Upregulation of H19 promoted SMC apoptosis in the aneurysm wall." (PMID 31989839, 2020). "The up-regulated expression profile of H19 could also be observed in human aneurysm tissue samples." (PMID 32219038, 2020). "Mechanistically, H19 increases the expression of HIF1α, leading to increased VSMC apoptosis in aneurysm." (PMID 35207478, 2022).
asthma (6 papers, 2020 to 2025). "And Low expression of H19 has been proposed as a protective mechanism in mouse models of asthma." (PMID 36188624, 2022). "H19 was found differentially expressed in OVA mice in our microarray analysis, thus, H19 could also potentially regulate inflammation of asthma by targeting goblet cells." (PMID 32929606, 2020). "Therefore, lncRNA CASC7/miR-21/PI3K/Akt axis and H19/miR-21/PTEN/Akt axis are potential therapeutic targets for asthma, and whether they can regulate T-cell differentiation to treat asthma needs further study." (PMID 35769905, 2022). "Therefore, H19 inhibition may alleviates the development of asthma by downregulating Muc5ac." (PMID 36188624, 2022).
breast adenocarcinoma (6 papers, 2007 to 2021). "Compared with healthy tissues, H19 is overexpressed in breast adenocarcinoma and is significantly associated with tumor values." (PMID 26136615, 2015). "On the other hand, the LncRNA H19 SNP is associated with the clinical course of certain types of adenocarcinoma including the breast adenocarcinoma and gastric adenocarcinoma and the effect of several LncRNA H19 SNP rs217727 on the susceptibility of LADC is also significant." (PMID 33799753, 2021). "As expected, we found upregulation of H19, IGF2 and HMGA1 following HMGA1P7 overexpression in MCF7 cells (human breast adenocarcinoma cell line)." (PMID 27874091, 2016).
cardiac ischemia (6 papers, 2019 to 2023). "Based on other studies showing H19 upregulation in aortic aneurysm and cardiac ischemia, as well as a study that found age‐related loss of imprint in rat liver, we also probed H19 expression changes in the liver, left ventricle, and ascending aorta." (PMID 31609547, 2019). "H19 has been reported to perform a function in modulating mitochondrial apoptosis in the process of cardiac ischemia-reperfusion injury via the miR-877-3p/Bcl-2 axis." (PMID 36787444, 2023).
cardiomyopathy (6 papers, 2018 to 2025). A disease of the heart muscle or myocardium proper. "Thus, loss of H19 is necessary to induce LOI cardiomyopathies." (PMID 34402430, 2021). "Thus, we conclude that loss of H19 lncRNA is sufficient to induce cardiomyopathy in adult mice." (PMID 34402430, 2021). "It has been reported that H19 is a primary miRNA precursor for microRNA-675, which is transcribed from the first exon of H19 and serves as the functional unit of H19 in several biological processes, such as tumorigenesis, invasion, and cardiomyopathy." (PMID 37508808, 2023). "To test the role of H19’s Mirlet7 binding in preventing cardiomyopathy, we used CRISPR/Cas9 genome editing to delete Mirlet7 binding sites in the H19 gene." (PMID 34402430, 2021). "In cardiomyopathy rat models, lncRNA H19 silenced DIRAS3 expression, promoted MTOR phosphorylation and inhibited autophagy in cardiomyocytes." (PMID 32301281, 2020). "Sprague-Dawley rats injected with STZ developed the cardiomyopathy of T1DM with decreased expression of cardiac H19." (PMID 30342478, 2018). "H19 has recently been identified as an important regulator of the cardiomyopathy of T1DM in experimental rats." (PMID 30342478, 2018). "Thus our results support a role for Mirlet7 miRNA binding to H19 lncRNA in preventing cardiomyopathies." (PMID 34402430, 2021). "In sum, H19/Igf2 LOI in mice results in transient neonatal cardiomegaly and then a progressive cardiomyopathy." (PMID 34402430, 2021). "That is, hearts from 6 month LOI mice carrying the H19 transgene are not enlarged as determined by heart weight/tibia length ratios (LOI = 12.9 ± 0.6 mg/mm, N = 3; LOI+ H19 BAC transgene = 11.5 ± 0.7, N = 3; p<0.05), are not fibrotic, and do not express cardiomyopathy markers." (PMID 34402430, 2021).
Cholestatic liver disease (6 papers, 2016 to 2023). "This study suggested that targeting cholangiocyte-derived exosomal H19 is a potential therapeutic strategy for the treatment of cholestatic liver diseases by modulation of hepatic inflammation." (PMID 31940841, 2020). "Targeting H19 represents a potential therapeutic target for cholestatic liver diseases." (PMID 34168124, 2021). "Since patients with liver cirrhosis have serum EVs carrying elevated levels of H19 compared to those from healthy individuals, H19-carrying EVs may play a critical role in the pathogenesis of cholestatic liver diseases and liver cirrhosis." (PMID 32154257, 2020). "Our study is the first to reveal a role of H19 in cholestatic liver disease." (PMID 26838806, 2016). "This study has demonstrated that SHP is a transcriptional repressor of H19, and overexpression of SHP and knockdown of H19 attenuated Bcl2-induced cholestatic liver injury in vivo, suggesting the association of H19 with SHP expression and cholestatic liver diseases." (PMID 32154257, 2020). "In conclusion, Cholangiocyte-derived exosomal H19 played a critical role in macrophage activation, differentiation, and chemotaxis through CCL-2/CCR-2 signaling pathways, which represent a therapeutic target for cholestatic liver diseases." (PMID 31940841, 2020).
dyslipidemia (6 papers, 2019 to 2025). "Regarding the association between clinical characteristics in the diabetic population and polymorphisms in the H19 gene, we found that reduced renal function and dyslipidemia were significantly correlated with the H19 SNP rs3741219 variant." (PMID 39898248, 2025). "Conversely, excess vitamin A induces epigenetic modifications (e.g., 18% hypermethylation of placental H19), perturbing fat‐muscle differentiation and increasing metabolic syndrome susceptibility." (PMID 40552338, 2025). "In contrast, our group identified low H19 expression in blood serum samples from patients with metabolic syndrome." (PMID 34298896, 2021). "The levels of serum TG, serum cholesterol, liver TG and liver cholesterol were significantly lower in H19-overexpressing mice, indicating improvements in dyslipidemia and fatty liver symptoms." (PMID 33115498, 2020).
embryonic carcinoma (6 papers, 2013 to 2024). "Inhibited H19 reduced the proliferation of human embryonic carcinoma cells (hECs) and embryonic stem (hES) cells." (PMID 38785917, 2024). "For example, H19 was shown to repress cellular growth in embryos and was also found to be a tumor suppresser in embryonic carcinoma." (PMID 26983719, 2016). "To study the role of H19 in oncogenesis and pluripotency, we down-regulated H19 expression in vitro and in vivo in pluripotent human embryonic carcinoma (hEC) and embryonic stem (hES) cells." (PMID 26415227, 2015). "However, the proliferation ability of H19 knockdown iPSCs was consistent with Zeira’s results regarding inhibited H19 reducing the proliferation of human embryonic carcinoma cells (hECs) and embryonic stem (hES) cells." (PMID 38785917, 2024). "Previous studies showed that both H19 and HULC are similar to ceRNAs in human embryonic kidney cells and human embryonal carcinoma cells by sponging let-7 and miR-372, respectively." (PMID 27809873, 2016).